LINC01258 (long independently transcribed non-coding RNA 1258)
Gene: Long non-coding RNA gene on chromosome 4 (38,420,662 to 38,523,180, reverse strand). Ensembl gene ENSG00000249534.
Diseases named in the same sentence as LINC01258 in open-access papers:
LINC01258 is named in the same sentence as 2 diseases in open-access papers, as found by Europe PMC text mining. Sharing a sentence is not in itself a finding about the gene and the disease. The quoted sentences say what the papers report.
type 1 diabetes (1 paper, 2022). "LINC01258 is upregulated in type 1 diabetes, a well-known immune disease." (PMID 36522672, 2022).
LINC01258 also shares sentences with these, for which no sentence is quoted: immune disease (1 paper).